RNU6-1193P (RNA, U6 small nuclear 1193, pseudogene)
Gene: Small nuclear RNA gene on chromosome 9 (64,380,194 to 64,380,300, forward strand). Ensembl gene ENSG00000238551.
Homologues: Orthologues: chimpanzee U6 (99% identical), macaque U6 (93% identical), dog U6 (70% identical), mouse Gm54642 (61% identical), mouse Gm22279 (59% identical), rat LOC120101210 (58% identical). Paralogues in human: RNU6-1269P (100% identical), RNU6-368P (100% identical), RNU6-538P (100% identical), RNU6-1320P (99% identical), RNU6-599P (99% identical), U6 (97% identical), U6 (96% identical), RNU6-316P (95% identical), RNU6-55P (95% identical), U6 (95% identical), RNU6-954P (94% identical), RNU6-821P (87% identical), and 1288 more.